CRP (C-reactive protein)
Diseases named in the same sentence as CRP in open-access papers (continued):
Sharing a sentence is not in itself a finding about the gene and the disease.
pericarditis (continued). "Patients with symptomatic RP and elevated CRP had rapid and sustained recovery after Rilonacept treatment, leading to a decrease in pericarditis annual recurrences and improvement in quality of life." (PMID 38399529, 2024). "The prerequisite for enrollment was the presence of an acute event in a patient with at least two recurrences of pericarditis along with CRP elevation." (PMID 38541631, 2024). "In the patients with pericarditis, the serum levels of CRP were elevated significantly, and IL-6 was increased dramatically in our cohort of MIS-C children with small pericardial effusion compared to those without." (PMID 38138278, 2023). "Moderate elevations have been reported in the initial presentations of acute pericarditis, and CRP can reach notably higher values (180 mg/dL)." (PMID 37873776, 2023). "The levels of CRP were significantly elevated in the children with pericarditis, 21.6 ± 13 mg/dL vs. 13.9 ±11 mg/dL, p = 0.035." (PMID 38138278, 2023). "Inflammatory biomarkers such as erythrocytesedimentation rate (ESR), white blood cells (WBC), and C-reactive protein (CRP)are increased in approximately 80% of patients having acute pericarditis,however overall sensitivity and specificity are low." (PMID 39077487, 2023). "The criteria for inclusion included: patients with more than two previous pericarditis recurrences, having elevated levels of C-reactive protein (CRP), being colchicine resistant, and being dependent on corticosteroids." (PMID 36505131, 2022). "Two patients diagnosed with pericarditis had normal troponin-T levels, but generally raised c-reactive protein (CRP) or erythrocyte sedimentation rate (ESR)." (PMID 36006288, 2022). "In patients with symptomatic RP with elevated CRP, rilonacept resulted in rapid and sustained reduction in patient-reported pericarditis pain and CRP." (PMID 33229362, 2020). "Rilonacept led to rapid and sustained improvement in pain, inflammation (CRP and pericarditis manifestations) and HRQOL." (PMID 33229362, 2020). "Increased CRP levels are common in patients with pericarditis, not only to confirm the suspicion, but also to monitor the disease activity." (PMID 32645077, 2020). "In symptomatic patients with elevated CRP >1 mg/dL (n=13) (parts 1 and 4), reductions in average pericarditis pain were observed as soon as after the first (loading) dose of rilonacept, and these decreases were maintained throughout the study." (PMID 33229362, 2020). "ESR and C-reactive protein are markers of inflammation and are frequently elevated in patients with acute pericarditis." (PMID 33364124, 2020). "Although, elevated C-reactive protein (CRP) is considered a confirmatory factor required for diagnosis of acute pericarditis; it is elevated in only 78% cases at presentation." (PMID 25861276, 2015). "It is important to avoid reducing the initial drugs doses too early, as this could lead to a reactivation of pericarditis while CRP levels are still high." (PMID 39798014, 2025). "D-D elevation was found in a significant proportion (50.6 to 73.3%) of patients diagnosed with acute pericarditis; increased values correlated with fever, higher CRP concentration, neutrophilic leukocytosis, lower haematocrit, higher platelet count and hospitalization." (PMID 39798014, 2025). "However, rheumatology was also consulted due to the patient’s lupus exacerbation as evidenced by elevated CRP, and believed that low-dose prednisone would be a better option to resolve the pericarditis, as it was secondary to a systemic autoimmune process." (PMID 40161164, 2025). "CRP may be inadequate in evaluating pericarditis with low-grade inflammation and may be normal in 15–20% of IRAP patients." (PMID 39798014, 2025). "Overall, 15–20% of cases of acute pericarditis have persistently normal CRP." (PMID 39798014, 2025).
pericarditis (continued). "Based on the available evidence, IL-1 blockers are mostly reserved for patients with the auto-inflammatory pericarditis phenotype (namely with striking CRP elevation, fever, and serositis), depicting recurrences despite an optimal treatment of pericarditis with first- or second-line agents." (PMID 38541631, 2024). "Studies have focused on the prognostic value of inflammatory markers in active pericarditis, suggesting that high-sensitivity C-reactive protein may affect the intensity and duration of pericarditis." (PMID 38455049, 2024). "Twenty-one patients with a clinical story of more than three pericarditis recurrences, laboratory evidence of CRP elevation above 1 mg/dL, colchicine resistance, and corticosteroid dependence received Anakinra 2 mg/kg/day (with a maximum dose of 100 mg) for 2 months." (PMID 38399529, 2024). "At present, suitable candidates for IL-1 blocker administration include patients with glucocorticoid-dependent colchicine pericarditis with frequent (≥2) relapses who depict an autoinflammatory phenotype (namely CRP elevation, fever, and pleuropulmonary involvement)." (PMID 39204174, 2024). "In contrast, patients presenting during the acute attack of pericarditis with low-moderate peak CRP levels along with the presence of a combination of arthritis, sicca syndrome, Raynaud phenomenon, and elevated serum autoantibodies are most probably affected by an autoimmune disorder." (PMID 38541631, 2024). "An RP event was defined as a return of pericarditis pain with an increase in C-reactive protein (CRP) level, as well as supportive objective evidence (e.g. pericardial effusion, pericardial rub, or electrocardiographic changes); each event was confirmed by an independent clinical-events committee." (PMID 39044797, 2023). "The levels of CRP were significantly elevated in the children with pericarditis (21.6 ± 13 mg/dL vs. 13.9 ± 11 mg/dL, p = 0.035), and the serum levels of IL-6 were higher in the children with small pericardial effusion compared to those without (191 ± 53 ng/L vs. 88 ± 27 ng/L, p = 0.041)." (PMID 38138278, 2023). "Recurring pericardial symptoms and persistent elevations in D-dimer and CRP point toward a COVID etiology, particularly in the absence of other factors associated with pericarditis." (PMID 35784959, 2022). "Importantly, recent findings showed how innate immunity plays a pivotal role in the pathogenesis of recurrent pericarditis with raised C-reactive protein, with inflammasome and IL-1 overproduction as drivers for systemic inflammatory response." (PMID 35350578, 2022). "However, previous studies have indicated that SLE-related acute pericarditis may be accompanied by a marked increase in CRP." (PMID 41383610, 2025). "Later, in 2020, the IRAP (International Registry of Anakinra for Pericarditis) study, a multicenter observational work, confirmed the efficacy and safety of Anakinra in the treatment of 224 colchicine-resistant and steroid-dependent patients affected by RP with high CRP values." (PMID 38399529, 2024). "Further labs showed an elevated CRP of 18.9 mg/dL, which, in conjunction with the pericardial rub and EKG results, led to the diagnosis of acute pericarditis." (PMID 40376326, 2025). "Inflammatory markers like C-reactive protein (CRP) and erythrocyte sedimentation rate (ESR) can point to inflammatory cardiac diseases, including pericarditis." (PMID 40091936, 2025). "The pro-inflammatory effects (increase in CRP and IL-6) and oxidative stress (MPO and ROS) intrinsic to ablation have been connected to early AF recurrence and pericarditis." (PMID 39156919, 2024). "We also found that in acute pericarditis the decline of hemoglobin levels correlated with neutrophilia and elevated NLR and CRP values." (PMID 39408004, 2024).
pericarditis (continued). "In 3 investigator‐assessed pericarditis recurrences, pain NRS scores were 4 or higher, but CRP remained below the RHAPSODY event adjudication criterion threshold of 1 mg/dL; 1 patient had a new pericardial effusion." (PMID 38471825, 2024). "However, the use of CRP does not apply in clinical practice as a specific diagnostic biomarker for aortic dissection, since increased levels can be observed in a number of other conditions (e.g., acute abdominal disease, pleuritis, pericarditis)." (PMID 35892496, 2022). "Outcomes: pericarditis pain (numeric rating scale (NRS)) and inflammation (C reactive protein (CRP)) for symptomatic patients; disease activity after CS taper for CS-dependent patients." (PMID 33229362, 2020). "The levels of high-sensitivity C-reactive protein (hs-CRP), interleukin(IL)-6 and tumor necrosis factor-α (TNF-α) were significantly elevated following surgery in the untreated pericarditis and atorvastatin groups compared with the control group (P<0.05)." (PMID 25524260, 2015). "If the initial result is negative in suspected pericarditis, we recommend to retest for CRP after 12–24 h." (PMID 39798014, 2025). "Elevated white blood cells, ESR and CRP observed in our patient are seen in all cases of acute pericarditis irrespective of etiology." (PMID 40722807, 2025). "Despite radiographic evidence of pericardial metastasis, the absence of diffuse ST-segment elevation characteristic of pericarditis and the non-persistent pattern of C-reactive protein dynamics argue against significant inflammatory pericardial involvement." (PMID 41164742, 2025). "However, neither a high fever of > 38 °C nor a clinically significant elevation in the CRP level was observed in this patient series, and it is unclear whether local (atrial) inflammation associated with pericarditis would lead to elevation of the glucose level." (PMID 36922617, 2023). "The inclusion criteria included recurrent pericarditis defined by at least two recurrences of symptoms, a pain numeric rating scale ≥4, C-reactive protein ≥1 mg/dl with concurrent use of nonsteroidal anti-inflammatory drugs (NSAIDs/colchicine/corticosteroids)." (PMID 36505131, 2022). "Baseline characteristics of patients with or without post-MI pericarditis (CMR evidence of LPE plus either elevated CRP and/or pericardial effusion)." (PMID 35282340, 2022). "Fifth, information regarding the history of recent infection, fever symptoms, and CRP levels was not available in our research, despite the potential of increasing differentiation between acute pericarditis and STEMI." (PMID 35887647, 2022). "Due to pericarditic chest pain, typical ECG findings and pericardial effusion with elevated C-reactive protein, the diagnosis of acute pericarditis was established, and a course of nonsteroidal anti-inflammatory drugs (NSAIDs) was initiated." (PMID 34067941, 2021). "One patient participated in the study twice: this patient successfully completed the study but, approximately 11 weeks after rilonacept discontinuation, developed a pericarditis recurrence (pain NRS 7/10; CRP 23.1 mg/dL) and cardiac tamponade requiring pericardiocentesis." (PMID 33229362, 2020). "The role of anakinra (IL-1 antagonist) is especially important in CS-dependent and colchicine-resistant pericarditis, antibody negative pericarditis followed by high levels of CRP, high fever, pleuropulmonary and systemic involvement." (PMID 31547038, 2019). "However, lower levels of hs-CRP, IL-6 and TNF-α were observed in the atorvastatin group compared with the untreated pericarditis group (P<0.05)." (PMID 25524260, 2015). "However, CRP-negative pericarditis is an interesting phenotype of IRAP which lacks such clear inflammatory characteristics, making it challenging to investigate and manage." (PMID 39798014, 2025).
pericarditis (continued). "Importantly throughout the entire base study and long‐term extension, there were no frank pericarditis recurrences with CRP elevation in patients on rilonacept in the absence of a treatment interruption." (PMID 38471825, 2024). "Additionally, CRP level, ESR and WBC were statistically higher in patients with recurrent pericarditis than with acute disease (CRP—160.57 ± 83.63 vs. 116.62 ± 49.57 mg/L, p = 0.05; ESR—72.0 ± 18.35 vs. 47.11 ± 15.67 mm/h, p < 0.001; WBC—19.32 ± 5.30 vs. 15.82 ± 3.64 × 109/L, p = 0.02)." (PMID 31547038, 2019). "To investigate whether pericarditis accompanying STEMI contributes to the re-elevation of the T-wave, we evaluated the time course of plasma CRP levels from the onset (day 0) through day 8 in another group of six patients with first anterior STEMI admitted to our hospital." (PMID 23263710, 2013).
Respiratory tract infection (72 papers, 2011 to 2025). An infection of the upper or lower respiratory tract. "This study aimed to investigate the effectiveness of MPV and C-reactive protein (CRP) measurements, which can be easily, widely, and quickly applied, in predicting the prognosis of respiratory tract infections caused by the H1N1 virus." (PMID 41578803, 2025). "CRP, in particular, has been a robust measure for improving the assessment of respiratory tract infections and increasing diagnostic certainty." (PMID 40891384, 2025). "As an additional diagnostic procedure, C-reactive protein (CRP) point-of-care testing (POCT) can reduce immediate antibiotic prescribing for respiratory tract infections (RTIs), the most common indications for antibiotic prescriptions in primary care." (PMID 35625187, 2022). "We show how it can be used in the design of a study to evaluate a point-of-care diagnostic test for C-reactive protein in out-of-hours primary care services, to guide antibiotic prescribing among patients presenting with possible respiratory tract infection." (PMID 35232491, 2022). "CRP levels >20 mg/dl were recognized only in 10 patients during natalizumab therapy and were mostly linked to respiratory tract infections." (PMID 30581413, 2018). "Preliminary findings suggest that the use of near-patient CRP testing may be associated with reduced antibiotic prescribing for respiratory tract infections, high levels of patient satisfaction and increased re-consultations." (PMID 21880122, 2011). "It re-iterates that the use of near-patient CRP testing may be associated with reduced antibiotic prescribing for respiratory tract infections and suggests it may be associated with high levels of patient satisfaction and increased re-consultations." (PMID 21880122, 2011). "Point-of-care (POC) tests for CRP are increasingly being used in primary care to assist general practitioners (GPs) in the diagnostic workup for various health complaints, including acute cough and abdominal pain, and to differentiate between mild and severe respiratory tract infections." (PMID 36662693, 2023). "Non-experts showed a greater interest in rapid microbiological testing, while the more experienced individuals relied not only on microbiological tests but also on CRP testing, as the latter provides a better prognosis for respiratory tract infections." (PMID 40921638, 2025). "One respondent said ‘we trialled CRP for RTI (respiratory tract infections) in primary care some years ago... some practices reduced antibiotic prescribing, some increased." (PMID 41409989, 2025). "GPs employed CRP-POCTs mainly for patients with respiratory tract infections (RTIs; 71.2% of all cases) and to a lesser extent for gastrointestinal infections (GIs; 10.4%)." (PMID 39159989, 2025). "CRP testing appears particularly valuable for triaging respiratory tract infections, and RADTs enable more targeted treatment of streptococcal pharyngitis." (PMID 41463788, 2025). "For example, if we take a hypothetical patient with a true CRP of 60 mg/L (a value in the middle of the equivocal group for recommending an antibiotic for respiratory tract infection), the CV from the data in this study is approximately 1.6." (PMID 41284612, 2025). "Professionals, in general, favour integrating these rapid microbiological POCTs for managing respiratory tract infections with other POCTs, such as CRP, and other complementary strategies like delayed antibiotic prescribing and communication skills training." (PMID 40921638, 2025). "One Dutch 3.5-year follow-up study after CRP implementation found that only 11 CRP tests were administered for 294 episodes of respiratory tract infection in the 203 patients in the CRP test group (3.7% of episodes)." (PMID 40887118, 2025). "GPs mainly used CRP-POCTs on patients with symptoms of respiratory tract infections (RTIs; 71.2% of all cases)." (PMID 39159989, 2025).